ALB (albumin)
Diseases named in the same sentence as ALB in open-access papers (continued):
Sharing a sentence is not in itself a finding about the gene and the disease.
dyslipidemia (continued). "We reported that pemafibrate significantly reduced the serum levels of AST, ALT and GGT and significantly increased serum albumin levels at 3, 6 and 12 months after the start of pemafibrate treatment in patients with hypertriglyceridemia (n = 246), with an improvement in atherogenic dyslipidemia." (PMID 37895151, 2023). "Furthermore, they were more likely to have metabolic syndrome and low levels of albumin." (PMID 36010180, 2022). "Our study results suggested that serum calcium or albumin-corrected calcium levels above 2.50 mmol/L in children might seem to be associated with the risk of dyslipidemia, although they failed to meet the clinical diagnosis cutoff value for hypercalcemia." (PMID 34434908, 2021). "The relationship between the presence of metabolic syndrome and adiponectin level was evaluated by multiple logistic regression analysis with adjustments for age, sex, smoking status, body mass index, hemoglobin, serum albumin, uric acid, phosphate, hs-CRP, UACR, and eGFR." (PMID 27895721, 2016). "Age, HT, DM, dyslipidemia, BMI, LVEF, albumin, WBC, neutrophil, CRP, NLR, NPAR, and CAR, which were statistically significant in the univariate analysis, were included in the multivariate analysis." (PMID 41153281, 2025). "Age, sex, metabolic syndrome, alcohol, Smoking, education, Charlson comorbidity index, MMSE score at baseline, serum albumin, apolipoprotein B/A1 ratio." (PMID 41262081, 2025). "The results of univariate logistic regression analysis indicated that the following factors were associated with DN: educational situation, finance, smoking, drinking, physical activity, dyslipidemia, GGT, statin use, Hba1c, BUN, SCR, ALP, GLB, and ALB." (PMID 38726340, 2024). "Our analysis revealed significant correlations between pre-surgery FSTL1 levels and total cholesterol, albumin, uricemia, and HDL values, indicating a link between FSTL1 and metabolic syndrome and inflammatory states." (PMID 38956222, 2024). "In our univariable logistic regression analysis, dyslipidemia, hemodialysis, previous IJV catheterization, preoperative angiotensin II receptor blocker, creatinine, albumin, and platelet count had p-values < 0.2." (PMID 33802444, 2021). "Because albumin is the most abundant serum protein produced by the liver, we reasoned that linking the expression of human PCSK9 to this promoter would induce a dyslipidemia similar to that observed in humans carrying PCSK9 gain-of function mutations." (PMID 30646909, 2019). "Metabolic syndrome was diagnosed in 273 patients (26.3%), whereas median CRP and albumin levels were 7 mg/L (range 1–23) and 4.4 g/L (range 2.6–5.8), respectively." (PMID 26496339, 2015). "Anthropometric characteristics, Albumin/Creatinine Ratio (ACR), Lipid profile, Liver enzyme concentration and occurrence of metabolic syndrome were compared between the two groups." (PMID 23283052, 2012). "We also determined whether any age-related changes in serum ALT were explained by metabolic syndrome components, adiposity-related biomarkers including leptin, adiponectin, ghrelin and interleukin-6 (IL-6), or other markers of hepatic function (bilirubin, albumin, gamma glutamyl transferase [GGT])." (PMID 21170382, 2010). "Of all patients with glomerular disease and dyslipidemia, 68% had low serum albumin compared to 40% of the non-glomerular group with dyslipidemia." (PMID 39940317, 2025). "In those without dyslipidemia, 53% of the glomerular group had low serum albumin compared to 43% of the non-glomerular group." (PMID 39940317, 2025). "With an increased level of free FAs not bound to albumin, the mode of their interaction with receptors changes, which can become one of the pathogenetic factors of non-alcoholic steatohepatitis and metabolic syndrome." (PMID 38542178, 2024). "There is no information on the association of the hemoglobin, albumin, lymphocyte, and platelet (HALP) score with dyslipidemia." (PMID 38004051, 2023).
dyslipidemia (continued). "The presence of microalbuminuria in the Blacks SS group is related to dyslipidemia by the non-esterified free fatty acids (NEFFA) albumin transport." (PMID 35930297, 2022). "Patients in the highest tertile were older, had more often CVD, were more often on dialysis treatment, had higher BMI and lower %HGS—and they were characterized by dyslipidemia with lower HDL and higher triglyceride as well as a high inflammatory burden with lower albumin and higher hsCRP." (PMID 33626087, 2021). "There were significant differences between the groups for age, frailty, smoking status, dyslipidemia, prior myocardial infarction and HF hospitalization, ABI, CLI, levels of hemoglobin and albumin, high-density lipoprotein cholesterol, triglycerides, and B-type natriuretic peptide." (PMID 34097103, 2021). "There is also a connection of the presence of metabolic syndrome and higher urinary albumin excretion in non-diabetic, essential hypertensive patients." (PMID 34638943, 2021). "The present data demonstrated that an ARB, olmesartan, could decrease urinary excretions of albumin, as well as AGT, suggesting that an ARB has albuminuria reduction effects in patients with metabolic syndrome." (PMID 27801805, 2016). "Our data demonstrate that olmesartan, an ARB, could decrease urinary excretions of albumin, as well as AGT in patients with metabolic syndrome." (PMID 27801805, 2016). "Based on the results of the present study, the association of TG/HDL-C with increased urinary albumin excretion and CKD was stronger in participants without dyslipidemia." (PMID 26607500, 2015). "Subjects with metabolic dyslipidemia (n = 17) had mean CSF Albumin Index 2.43 units higher than those without (n = 19) (P = 0.48)." (PMID 22654903, 2012). "Subjects with atherogenic dyslipidemia (n = 15) had mean CSF Albumin Index 2.69 units higher than those without (n = 21) (P = .029)." (PMID 22654903, 2012). "Our multivariable analysis showed that the strongest predictors of postoperative complications were patient-related factors—age, dyslipidemia, and early postoperative biochemical changes (delta sodium, albumin, and direct bilirubin)—rather than the use of 3D modeling." (PMID 41464562, 2025). "We should highlight that in our study it was not possible to evaluate urinary albumin excretion and/or urinary albumin/creatinine ratio, and therefore the number of patients with metabolic syndrome may be underestimated according to the WHO criteria." (PMID 39841720, 2025). "Therefore, the increased albumin levels observed with OMWW-OL could correlate with the anti-inflammatory activity of this olive byproduct and contribute to some extent to metabolic syndrome prevention." (PMID 39339668, 2024). "We also did not measure oxidized albumin levels, which could have had an impact on our results, as it is shown to be related with augmented oxidative stress and metabolic syndrome." (PMID 29298330, 2018). "In our study, modest decreases in albumin and GGT and increases in bilirubin were observed with increasing age after adjustments for sex, alcohol use, metabolic syndrome traits, and surrogate markers of adiposity, suggesting that a decrease in liver function may indeed be present." (PMID 21170382, 2010). "Moreover, multiple low-frequency and rare GCKR variants were found to contribute to various aspects of cardiometabolic traits, such as serum triglyceride and albumin levels and metabolic syndrome, in this Taiwanese population, independent of the rs1260326 variant." (PMID 35328045, 2022). "And low-certainty evidence suggests that body weight, sex, sex & body weight, dyslipidemia, visual field deficits, platelet count, UA, DBP, albumin, WMH and time from onset to treatment (OTT) were not statistically significant." (PMID 36918881, 2023).
dyslipidemia (continued). "In obese individuals with metabolic syndrome, two common characteristics of CKD, 12 weeks of aerobic exercise training significantly reduced albuminuria (urinary albumin), compared to a no-exercise control group." (PMID 26090382, 2015).
liver dysfunction (258 papers, 2007 to 2026). "On the one hand, the decrease in TF and TIBC was associated with the reduction in ALB and the prolongation of PT, indicating that liver dysfunction in PLA leads to insufficient synthesis of TF, which in turn caused a decrease in TIBC." (PMID 41280746, 2025). "We also measured plasma albumin levels in the mice because it is often associated with liver dysfunction, inflammation, and disease." (PMID 39514172, 2024). "The serum cholinesterase indicates liver function and is closely associated with the synthesis of albumin in the liver and is a well-known marker of liver dysfunction." (PMID 39049017, 2024). "Parameters of liver dysfunction (low albumin), often associated with chronic poor‐health, was also associated with decreased HRQoL." (PMID 37984378, 2024). "Univariate analysis revealed that severe postoperative liver dysfunction was significantly associated with lower albumin-bilirubin scores (ALBI ≥ -2.6; P = 0.032)." (PMID 37072727, 2023). "Reduced protein concentrations are interpreted as a surrogate marker of plasma albumin concentrations and have been associated with mortality in patients with pancreatitis, infection, trauma, burns, and liver dysfunction." (PMID 37362407, 2023). "The albumin–bilirubin (ALBI) score incorporates albumin and bilirubin to subdivide patients with well-compensated underlying liver dysfunction (Child–Pugh score A) into two distinct groups." (PMID 35216045, 2022). "Aspartate aminotransferase/platelet ratio index (APRI) and albumin–bilirubin grade (ALBI) are validated prognostic indices implicated as predictors of postoperative liver dysfunction after hepatic resection." (PMID 33609383, 2021). "A high INR was also associated with decreased ALB, commonly regarded as an indicator of liver dysfunction and poor nutrition status, in both cohorts (both P < 0.05)." (PMID 34433454, 2021). "As a subsequent outcome, the improved fatty acid metabolism in liver with Met supplementation reduces the risk of liver dysfunction, an idea supported by the biomarkers of liver function (e.g. greater albumin and VLDL, and lower bilirubin) in OVE + SM cows." (PMID 28191311, 2017). "On multivariate analysis, transfusion showed a strong association with the development of liver dysfunction, followed by number of segments resected, number of medical comorbidities, and preoperative abnormalities in bilirubin and albumin." (PMID 25667141, 2015). "Given the dose-dependent effect of 6PPD-Q, it can be speculated that pregnant women may potentially be at greater risk by developing additional liver dysfunctions such as reductions in albumin and urea production." (PMID 40832469, 2025). "Interestingly, decreased albumin, indicating liver dysfunction, was uniquely linked to inferior TTCS in multi-variate analysis as the strongest independent prognostic factor (HR = 6.26)." (PMID 41429572, 2025). "Specifically, albumin is considered a critical biomarker closely related to renal function and may decrease in conditions associated with liver dysfunction." (PMID 40101226, 2025). "serum albumin and aspartate transaminase levels as predictors of severity for scrub typhus and we hypothesized that greater degree of liver dysfunction is associated with severe disease and poor outcome." (PMID 38357080, 2024). "Prior studies have shown low creatinine levels to be an independent predictor of in-hospital mortality, suggesting liver dysfunction but when found in association with normal albumin levels; physical deconditioning or muscle wasting has been suggested as the cause." (PMID 38535308, 2024). "Additionally, FBG, CR, TB, ALB, lactate, serum phosphorus, liver dysfunction and shock are risk factors for death of septic patients." (PMID 38669099, 2024). "Moreover, serum cholinesterase is closely associated with the synthesis of albumin in the liver and is a well-known marker of liver dysfunction." (PMID 39049017, 2024).
liver dysfunction (continued). "Both irreversible binding (resulting in loss of binding capacity) and an indication of liver dysfunction could explain the positive correlation between albumin levels and busulfan CL." (PMID 38276491, 2023). "ALB is produced mainly by the liver and the rise of ALB concentration may be associated with liver dysfunction." (PMID 37559889, 2023). "In accord with the literature, low albumin and intestinal dysbiosis with an altered gut–immune–liver axis as a marker of liver dysfunction could be associated with the poor outcomes after CRS." (PMID 35814748, 2022). "Liver dysfunction is associated with reduced serum albumin levels, implying that concentrations and pharmacological effects of unbound HSK3486 may be elevated in subjects with mild or moderate hepatic impairment." (PMID 36217101, 2022). "In the perioperative period, albumin loss, increased capillary permeability, intravenous infusion dilution, and liver dysfunction might be the primary causes of reduced albumin levels in patients." (PMID 35252328, 2022). "Low level of albumin in non‐survivors might be attributable to intubation induced inadequate intake, reduced synthesis caused by liver dysfunction and increased consumption due to organ damage." (PMID 32914892, 2020). "Decreased serum albumin is strongly associated with aging and reflects inflammation, frailty, and several pathological conditions, including cancer, rheumatoid arthritis, and liver dysfunction." (PMID 27276092, 2016). "This limitation is likely not significant based on our previous report that soybean oil parenteral nutrition was associated with significant liver dysfunction, as indicated by higher serum total bilirubin, direct bilirubin, and γ-GT and lower serum albumin levels compared to control." (PMID 25918521, 2015). "Furthermore, the low level of ALB correlated with degree of the loss of vascular integrity, enhanced vascular permeability and liver dysfunction." (PMID 24587001, 2014). "Albumin can be sequestered in tissues with edema, secondary to inflammation and increased capillary permeability, hemorrhages, low protein production due to concomitant hepatopathy, and can also be related to protein loss through the urine due to glomerulopathies." (PMID 39774740, 2024). "In addition to IL6, low albumin (HR 3.0, [95% CI 1.4–6.3]; p = 0.003), high total bilirubin values (HR 4.4, [95% CI 2.2–9.0]; p < 0.001), and higher mALBI grade (HR 3.9, [95% CI 1.9–8.1]; p < 0.001) were associated with shorter time-to-liver dysfunction." (PMID 34080071, 2021). "Plasma albumin levels are known to be lower in the elderly than in the young due to age-related liver dysfunction, which reduces the protein synthesis capacity." (PMID 40507037, 2025). "For example, activated C3 drives inflammation, high TP levels indicate hemoconcentration from decreased serum water content (e.g., severe dehydration from diarrhea), low ALB and high bile acids suggest liver dysfunction." (PMID 40545549, 2025). "The median albumin concentration in the control group was approximately 4.2 g/dL, suggesting a potential protective factor against liver dysfunction." (PMID 40647574, 2025). "Elevated cholesterol and reduced albumin levels in blood suggest metabolic stress and early liver dysfunction in a sex-dimorphic fashion." (PMID 40910069, 2025). "In critically ill patients, especially those with AKI, albumin levels often decline due to multiple factors including malnutrition, liver dysfunction, systemic inflammation, and hemodilution secondary to fluid overload." (PMID 40748973, 2025). "Studies have confirmed that severe IRI during LT causes significant postoperative changes in lab results, especially CRP and ALB, affected by liver dysfunction and stress." (PMID 40705850, 2025). "Albumin is primarily synthesized by the liver, and patients with chronic heart failure often have liver dysfunction or liver damage." (PMID 40104144, 2025).
liver dysfunction (continued). "A decrease in albumin levels typically signifies poor nutritional status or liver dysfunction, as well as the exacerbation of systemic inflammatory responses." (PMID 40735448, 2025). "The AST/ALT ratio, serum albumin, and bilirubin levels also have prognostic value for severe dengue, with elevated AST/ALT ratios linked to early mortality risks, highlighting liver dysfunction as a key feature in severe dengue episodes." (PMID 40573331, 2025). "In terminally ill patients, albumin levels are profoundly affected by processes such as hypercatabolism, chronic systemic inflammatory response, and liver dysfunction secondary to multiorgan failure." (PMID 39859129, 2025). "In turn, lower albumin, cholesterol, and PON in the blood of animals have been associated with liver dysfunction or impairment." (PMID 41514704, 2025). "Although severe hepatic impairment is less common, even mild liver dysfunction can reduce albumin production." (PMID 39408980, 2024). "Elevated lactate levels or reduced albumin levels indicate liver dysfunction, making the LAR a more accurate reflection of liver metabolism." (PMID 39767157, 2024). "KS males have mild liver dysfunction reflected by a significant increase in the main liver markers and decrease in albumin." (PMID 38816662, 2024). "Specifically, they showed greater liver dysfunction, indicated by elevated levels of transaminases, bilirubin, international normalized ratio, and lower albumin levels (p < 0.05)." (PMID 39434907, 2024). "An increase in liver transaminases and bilirubin and a decrease in albumin and coagulation factors are classical laboratory findings suggesting chronic generalized liver dysfunction." (PMID 39064571, 2024). "Other factors influence TAC pharmacokinetic variability, particularly liver dysfunction, gastrointestinal motility disorders, food and/or drug interactions, hematocrit, albumin concentration, and renal function." (PMID 38674430, 2024). "Albumin levels are markedly correlated with liver dysfunction and are used in many medical calculators regarding liver transplant and prognosis." (PMID 38541088, 2024). "Pesticides can cause liver damage and induce liver dysfunction, including changes in ALT, AST, ALP, serum bilirubin, total protein, and albumin, which are commonly used as liver function tests." (PMID 37505536, 2023). "The InT group had severe schistosomiasis-liver dysfunction, with a severe drop in serum albumin and a considerable increase in serum AST and ALT." (PMID 37964174, 2023). "A decrease in albumin concentration, as observed in paclitaxel-administered rats, indicated insufficiency of albumin synthesis by the liver due to hepatopathy." (PMID 37275575, 2023). "Herein, CdCl2 induced liver enzyme synthesis while decreasing the albumin and total protein content compared to the control indicating liver dysfunctions." (PMID 37760855, 2023). "In a study on liver tissue from patients at different stages of decompensation, HNF-4α expression was downregulated and correlated with liver dysfunction, fibrosis stage, and prognostically relevant serum parameters bilirubin, albumin, and prothrombin time." (PMID 36652164, 2023). "Laboratory data showed normal leucocytes, increased creatine kinase isoenzyme, and decreased albumin with liver dysfunction in most patients." (PMID 38264056, 2023). "In light of these findings, it is deemed unlikely that the observed decreases in albumin are a result of hepatopathy, although the complex physiological relationship of this parameter with multiple body systems hinders accurate interpretation." (PMID 35902827, 2022). "In particular, changes in coagulation parameters, elevated bilirubin as well as decreased albumin are indicative of preoperatively liver dysfunction." (PMID 36233670, 2022). "Serum bilirubin, albumin, and coagulopathy were the primary parameters that were found to indicate the severity of liver dysfunction." (PMID 35545763, 2022).